SMTN (smoothelin)
Description:
Structural protein of the cytoskeleton.
Tractability: PROTAC: ubiquitination databases record sites on it.
Gene: Protein-coding gene on chromosome 22 (31,064,105 to 31,104,757, forward strand). Ensembl gene ENSG00000183963.
Subcellular location: Cytoplasm, cytoskeleton
Subcellular location (Human Protein Atlas): Nucleoplasm; Actin filaments
Gene Ontology:
Molecular function: actin binding; structural constituent of muscle
Biological process: actin cytoskeleton organization; muscle organ development; smooth muscle contraction
Cellular component: actin cytoskeleton; nucleoplasm; cytoskeleton
Genetic constraint (gnomAD): Loss-of-function variants: 58 observed, 97.74 expected, observed/expected ratio (o/e) 0.59, 90% interval 0.48 to 0.74. The upper end of that interval is the gene's LOEUF score, 0.74, which puts it in group 3 of 6, group 1 being the genes least tolerant of losing a copy. Missense variants: 1,185 observed, 1,237.9 expected, observed/expected ratio (o/e) 0.96, 90% interval 0.91 to 1. Synonymous variants: 478 observed, 494.12 expected, observed/expected ratio (o/e) 0.97, 90% interval 0.9 to 1.04.
Homologues: Orthologues: chimpanzee SMTN (96% identical), macaque SMTN (94% identical), dog SMTN (88% identical), rabbit SMTN (85% identical), pig SMTN (84% identical), guinea pig SMTN (82% identical), rat Smtn (81% identical), mouse Smtn (79% identical), tropical clawed frog smtn (46% identical).
Diseases named in the same sentence as SMTN in open-access papers:
SMTN is named in the same sentence as 24 diseases in open-access papers, as found by Europe PMC text mining. Sharing a sentence is not in itself a finding about the gene and the disease. The quoted sentences say what the papers report.
atherosclerosis (2 papers, 2022 to 2023). A disease characterized by the build-up of fatty material and calcium deposition in the arterial wall resulting in partial or complete occlusion of the arterial lumen. "Therefore, we speculate that MYLK and SMTN reduce CD56 + NK cell involvement in the occurrence and progression of atherosclerosis." (PMID 37963970, 2023).
Hypertension (2 papers, 2020 to 2023). The presence of chronic increased pressure in the systemic arterial system. "Expression of OGT, C8orf33, DGKA and SMTN has been correlated with cardiovascular disease, hepatocellular carcinoma, acute myeloid leukemia and hypertension, respectively." (PMID 37026480, 2023). "Indoxyl sulphate: Parallel to inducing vascular calcification, indoxyl sulphate administration to human VSMC or rats with hypertension or 5/6 nephrectomy increased the expression of CBFA1/RUNX2, ALP, BMP2 and osteopontin, while a reduction in α-SMA, SM22-α and/or SMTN expression could be observed." (PMID 33172085, 2020).
benign leiomyomas (1 paper, 2025). "Studies examining smoothelin’s utility in smooth muscle tumors of the gastrointestinal tract, uterus, and other soft tissues have indicated that cytoplasmic expression is highly sensitive and specific for benign leiomyomas." (PMID 39836188, 2025).
colorectal cancer (1 paper, 2008). A primary or metastatic malignant neoplasm that affects the colon or rectum. "Interestingly, SMTN gene mutations have recently been identified in colorectal tumors, and the gene has been suggested as a candidate colorectal cancer gene." (PMID 18534021, 2008).
esophageal cancer (1 paper, 2020). A primary or metastatic malignant neoplasm involving the esophagus. "Based on TCGA database and literature search, we analyzed the methylation of KCNA3, USP44, OPLAH and SMTN in esophageal cancer." (PMID 32266120, 2020).
keloid (1 paper, 2007). An irregularly shaped, elevated mark on the skin caused by deposits of excessive amounts of collagen during wound healing. "Elevated expression of DES, MYH11, MYL9 and SMTN in leiomyomas and several KRTs in keloids and scars reflects the cellular composition of these tissues." (PMID 17718906, 2007).
metabolic syndrome (1 paper, 2021). A cluster of metabolic risk factors for CARDIOVASCULAR DISEASES and TYPE 2 DIABETES MELLITUS. "The pathophysiology of metabolic syndrome-associated OAB includes increased oxidative stress, altered regulation of postsynaptic receptors, dysregulation of smoothelin, and enhanced programmed cell death." (PMID 34210091, 2021).
pterygium (1 paper, 2021). A wedge-shaped fibrovascular lesion arising from the bulbar conjunctiva and extending to the cornea. "In addition, analyzing the expression of CALD1, DES, and SMTN, which are three known markers of smooth muscle cells being absent in myofibroblasts, revealed a significant downregulation or comparable expression in pterygium samples when compared to healthy conjunctiva." (PMID 35174178, 2021).
tumor (4 papers, 2008 to 2023). "Our work provides several advantages over previous studies: the single expression of COL11A1 is able to predict MP infiltration, and it is a nondependent MP presence marker (as smoothelin) because it is tumor stromal marker." (PMID 37760937, 2023). "TCGA-A tumours showed higher expression of most group I/FTEC epithelial proteins such as KRT7, MSLN, CDH6, ASS1 and EPCAM, while TCGA-B tumours had higher expression of the group III/IOSE mesenchymal proteins ITGA5, HMOX1, SMTN and GJA1 (refs 7, 34)." (PMID 27561551, 2016). "Some whole-tumor chips of TUR material may contain detrusor muscle fibers that are not easy to detect without special immunostains like smoothelin." (PMID 26791567, 2016).
SMTN also shares sentences with these, for which no sentence is quoted: cancer (2 papers); acute myeloid leukemia (1); adenomyosis (1); benign tumors (1); bladder cancer (1); breast carcinoma (1); cardiovascular disease (1); colorectal tumors (1); gastric cancer (1); heart failure (1); hepatocellular carcinoma (1); prostate carcinoma (1); sarcopenia (1); smooth muscle tumor (1); Wernicke encephalopathy (1).